IGKV1D-12 (immunoglobulin kappa variable 1D-12)
Description:
V region of the variable domain of immunoglobulin light chains that participates in the antigen recognition. Immunoglobulins, also known as antibodies, are membrane-bound or secreted glycoproteins produced by B lymphocytes. In the recognition phase of humoral immunity, the membrane-bound immunoglobulins serve as receptors which, upon binding of a specific antigen, trigger the clonal expansion and differentiation of B lymphocytes into immunoglobulins-secreting plasma cells. Secreted immunoglobulins mediate the effector phase of humoral immunity, which results in the elimination of bound antigens. The antigen binding site is formed by the variable domain of one heavy chain, together with that of its associated light chain. Thus, each immunoglobulin has two antigen binding sites with remarkable affinity for a particular antigen. The variable domains are assembled by a process called V-(D)-J rearrangement and can then be subjected to somatic hypermutations which, after exposure to antigen and selection, allow affinity maturation for a particular antigen.
Synonyms: IGKV1D12; L19
Tractability: Antibody: its Gene Ontology location is reachable by antibodies, with high confidence; UniProt places it where antibodies can reach, with medium confidence; UniProt predicts a signal peptide or a membrane-spanning region.
Gene: Immunoglobulin variable (V) gene on chromosome 2 (90,159,840 to 90,160,335, forward strand). Ensembl gene ENSG00000278857.
Subcellular location: Secreted; Cell membrane
Pathways (Reactome):
Immune System: Antigen activates B Cell Receptor (BCR) leading to generation of second messengers; CD22 mediated BCR regulation; Classical antibody-mediated complement activation; FCERI mediated Ca+2 mobilization; FCERI mediated MAPK activation; FCERI mediated NF-kB activation; FCGR activation; Fc epsilon receptor (FCERI) signaling; Immunoregulatory interactions between a Lymphoid and a non-Lymphoid cell; Initial triggering of complement; Regulation of Complement cascade; Regulation of actin dynamics for phagocytic cup formation; Role of LAT2/NTAL/LAB on calcium mobilization; Role of phospholipids in phagocytosis
Disease: FCGR3A-mediated IL10 synthesis; FCGR3A-mediated phagocytosis; Potential therapeutics for SARS
Hemostasis: Cell surface interactions at the vascular wall
Vesicle-mediated transport: Scavenging of heme from plasma
Gene Ontology:
Molecular function: antigen binding
Biological process: immune response
Cellular component: blood microparticle; extracellular exosome; extracellular region; immunoglobulin complex; plasma membrane
Homologues: Orthologues: mouse Igkv15-103 (74% identical). Paralogues in human: IGKV1-12 (99% identical), IGKV1D-16 (92% identical), IGKV1-39 (91% identical), IGKV1-9 (91% identical), IGKV1D-13 (91% identical), IGKV1D-39 (91% identical), IGKV1-16 (90% identical), IGKV1-17 (90% identical), IGKV1-27 (89% identical), IGKV1-5 (88% identical), IGKV1-6 (88% identical), IGKV1D-17 (87% identical), and 81 more.